TNC (tenascin C)
Diseases named in the same sentence as TNC in open-access papers (continued):
Sharing a sentence is not in itself a finding about the gene and the disease.
tumor (continued). "Key ECM targets such as tenascin-C (TN-C) have been recently found to be overexpressed in DMG tumours compared to normal brain tissue." (PMID 34944870, 2021). "The cell adhesion molecule Tenascin C (TNC) has been shown to positively regulate tumor proliferation via TAMs." (PMID 33766119, 2021). "Yong and co-workers also described that brain tumour-initiating cells can secrete TnC in exosomes and suppress T-cell activation, enabling tumor progression and metastasis through the modulation of antitumor immunity." (PMID 33981316, 2021). "To find any association of IFN signaling in tumor cells with mesenchymal phenotypes, we chose five well-established signature genes of the mesenchymal phenotype: CHI3L1, CD44, SERPINE1, TNC, and TIMP1." (PMID 34771447, 2021). "When stained for tenascin-C, the tumour-free nodes in both groups were variable, with some showing minimal expression and others containing regions of strong, diffuse stromal staining." (PMID 34564696, 2021). "Due to their importance and multi-functions with respect to the ECM, we further analyzed the effect of tumor treatment with si-hVDAC1-2A on the expression of periostin and tenascin C." (PMID 34200480, 2021). "Some components repelled certain cell types, for example, TGFBI, which decreased cell attachment of fibroblasts, and lumican and tenascin C, which reduced attachment of tumor cells." (PMID 34884982, 2021). "While tenascin C expression is restricted to connective tissues and stem cell niches in adult tissues, it is very prominent in tumor tissues." (PMID 34200480, 2021). "In conclusion, this work presents clinical evidence of the lymph node pre-metastatic niche and establishes tenascin-C as a feature of the niche prior to the arrival of tumour cells." (PMID 34564696, 2021). "The expression levels of periostin and tenascin C were analyzed by IF of sections from si-hVDAC1-2A-TTs and si-NT-TTs to evaluate protein levels in the tumor." (PMID 34200480, 2021). "The increased local concentration of VEGF within the GBM TME results in upregulation of periostin and tenascin C within blood vessels trapping T cells and preventing tumor penetrance." (PMID 33178210, 2020). "As adenocarcinoma progresses, Nkx2-1 expression decreases, releasing the suppression of Tenascin-C expression, which is thought to feed into accelerating tumor progression and metastasis." (PMID 33014869, 2020). "Glycoproteins, such as osteopontin, periostin and tenascin C are deposited either by infiltrating tumour cells or by stromal cells at the metastatic site and are important for the colonisation of tumour cells by inducing stemness-like signalling pathways." (PMID 33037194, 2020). "Reassuringly, several known CRC biomarkers, such as S100A9 and Tenascin-C, were found to be overexpressed in the tumor tissues by our mass spectrometric approach." (PMID 32166002, 2020). "In LAPC9 tumors, the TNC protein is expressed in the tumor-adjacent ECM and in the proximity of vessels (intact and castrated) and co-expressed by smooth muscle actin (αSMA)- and collagen type I-positive myofibroblasts." (PMID 33334054, 2020). "In particular, 91-amino acid alternatively spliced type-III homology domain of Tenascin-C FnIII C (TNC-C) has a tumor-restricted expression pattern." (PMID 32242067, 2020). "In summary, we revealed an overexpression of ECM components, which are associated with enhanced migratory capacities of tumour cells (TNC, FN1), resistance to chemotherapy (COL11A1, SPP1) and adverse outcome (COL11A1, TNC, FN1) in other primaries." (PMID 32878206, 2020). "Occasionally, low-grade adenocarcinomas (grade IV) exhibited focal random expression of Tenascin C in tumor cells and extracellular matrix, which was reversely correlated to the loss of Nkx2.1 in these tumor cells indicative of tumor progression." (PMID 32994412, 2020).
tumor (continued). "Changes in the TNC isoforms expression pattern have been then described in a number of malignancies, and their nature appears to be tumor-type specific." (PMID 32817625, 2020). "Genes specifically expressed by tumor cells, like tenascin C (TNC), periostin and TIMP1 (Tissue inhibitor of metalloproteinases 1) can shape the brain parenchyma." (PMID 32570988, 2020). "TNC appears to have supportive roles in tumor growth, metastasis, tumor angiogenesis, and inhibition of immune surveillance." (PMID 32322169, 2020). "Here, the authors show that autophagy is reduced in TNBC, which results in an increase in Tenascin C and reduced activation of tumour infiltrating lymphocytes." (PMID 32732922, 2020). "More importantly, inhibition of Tenascin-C in autophagy-impaired TNBC cells sensitizes T cell-mediated tumour killing and improves antitumour effects of single anti-PD1/PDL1 therapy." (PMID 32732922, 2020). "Tumor thickness and VEGF expression increased in hyalograft-based tumor models, whereas expression of laminin-332, tenascin C, and hypoxia-inducible factor 1α was lower than in collagen-based models." (PMID 33344431, 2020). "These tumor-stroma interactions are facilitated by the glycoprotein podoplanin and the extracellular matrix protein tenascin-C expressed by CAFs." (PMID 33747899, 2020). "While this complicates the characterization of tenascin-C in tumor stroma, it has led to the development of prospective isoform-specific tumor therapies." (PMID 33692777, 2020). "There is a large body of literature that highlights the role of TNC in tumor expansion and metastasis." (PMID 32817625, 2020). "We observed that TNC knockout significantly reduced the tumour burden, as confirmed by the growth curves of the xenograft tumour volumes and the tumour weights in syngeneic BALB/c mice." (PMID 32732922, 2020). "In vitro, tenascin-C promotes the proliferation and migration of many tumor-derived cell lines and there are reduced metastases in tenascin-C knockout mice and in mice lacking factors that promote the expression of tenascin-C." (PMID 33692777, 2020). "A high podoplanin and tenascin-C expression in the stroma of PCa biopsies strongly correlates with tumor stage, lymph node metastasis, and poor prognosis." (PMID 33747899, 2020). "Reassuringly, several known CRC biomarkers, such as CEA, S100A9, and tenascin C, were among those overexpressed in the tumor tissues in our findings, validating our experimental approach." (PMID 32587829, 2020). "It has been shown that TNC in tumor cells binds to the syndecan-4 binding site in fibronectin, thereby blocking syndecan-4 ligation, releasing the tumor cells from the suppressive effect of fibronectin on their proliferation." (PMID 32817625, 2020). "Third, we detected the expression of SMA, TGF-beta and tenascin C, indicating the applicability of our model for studying tumour-stroma interactions." (PMID 31138877, 2019). "Several genes splicing events, including KIAA1715/56096/AP, ZNF567/49415/AP, NTMT1/87861/AP, ANAPC15/17570/AD, SRPK2/81284/ES, MTMR11/7413/AP, FNIP2/70999/AP, and TNC/87336/ES, differed significantly between tumor and normal samples." (PMID 31552163, 2019). "Positive features of TNC expression were mainly localized in the cytoplasm of tumor cells and extracellular matrix." (PMID 30633201, 2019). "Binding of tenascin C to fibronectin weakens cell adhesion as it interferes with syndecan-4 and integrin α5β1 interactions to fibronectin, resulting in enhanced tumor cell proliferation." (PMID 31137693, 2019). "Although increasing evidence demonstrates that TNC and MALAT1 function in tumour behaviours, their connection and underlying mechanisms in regulating ES tumour progression remain to be elucidated." (PMID 31649319, 2019).
tumor (continued). "Tenascin-C variant molecules containing the type III-A2 domain have therefore been implicated in tumorigenesis and tumor progression, while the substantial role of these variants in oncogenic transformation and malignant progression has remained elusive." (PMID 31261783, 2019). "It is worth noting that both serum S100A9 and TNC levels exhibit a significant increase in CRC patients with tumor metastasis (p=0.025; p=0.085)." (PMID 31632476, 2019). "In particular, susceptibility to metastasis is associated with tumor cell-derived deposition of certain ECM proteins, such as tenascin C (TNC) in the metastatic niche." (PMID 31552050, 2019). "Osteosarcoma metastasis to the lungs is dependent on TNC expression and the respective expression a receptor on tumor cell α9β1 integrin." (PMID 31552050, 2019). "Histologic analysis of brain specimens from xenografts demonstrated a significant decrease in tumor volume after TNC-knockdown at 25 days post implantation (black arrows indicate tumor location) (***p < 0.001)." (PMID 31754182, 2019). "Although tenascin-C and tenascin-W are often overexpressed in tumor stroma, there is now good evidence that the expression of tenascin-W is much more tumor-specific than the expression of tenascin-C." (PMID 31032255, 2019). "TNC is a ligand for β1- and β3-integrin and its accumulation in the lungs promotes tumor cell outgrowth and metastasis." (PMID 31552050, 2019). "Immunohistochemistry and pathological data have demonstrated an increased expression of TNC in tumor tissues of colon and prostate." (PMID 31798767, 2019). "Tenascin-C is a tumor-specific extracellular matrix highly expressed in most solid tumors and mainly secreted by CAF." (PMID 30871158, 2019). "β6 was shown in the basal lamina, cell membrane, and cytoplasm, while tenascin-C was shown in the cytoplasm of the tumor cells." (PMID 29584696, 2018). "Tenascin-C appears to be involved in the metastatic process and is often found at the tumours leading edge, it plays a role in epithelial-to-mesenchymal transition (EMT) and has also been shown to block T cell activation." (PMID 29416729, 2018). "The expressions of laminin-5, a ligand for β4, and tenascin-C, a ligand for β6, were observed in both the cytoplasm of tumor cells and the stroma within tumor tissues, but were predominantly observed within tumor cells." (PMID 29584696, 2018). "Tenascin C facilitated tumor localization of liposomal formulation by specifically inducing CAF apoptosis (at a very low dose 5 mg/kg), by reducing interstitial fluid pressure and vascular normalization." (PMID 30429787, 2018). "Nevertheless, the expression of Tenascin-C in both tumour samples further links the Clival GCT to the GCT of long bones, where its intense expression in the extracellular matrix has been clearly described by us and others." (PMID 29609578, 2018). "Tenascin C has been identified as a predicted target of miR-198, one of the top 10 miRNAs downregulated in tumor stroma of CRCs with synchronous liver metastasis." (PMID 30282914, 2018). "The presence of tenascin-C within tumor infiltrated tissues made it as an attractive candidate for antibody mediated therapy." (PMID 29515769, 2018). "Given the significant expression of the glycoprotein Tenascin-C in GCT patients and its association with local relapse, we also evaluated its immunohistochemical expression in both tumour biopsies." (PMID 29609578, 2018). "Tenascin C plays an important role in inflammatory and fibrotic processes, tumor angiogenesis and as an immunomodulator in cancer." (PMID 29868474, 2018). "For instance, the AS of tenascin-C is triggered by low pH in normal cells, and this is an effect of nearby tumor growth." (PMID 28493890, 2017). "In this study we set out to decipher the functional interplay of TNC and FN in tumour angiogenesis at the level of endothelial cells." (PMID 28986537, 2017).
tumor (continued). "For example, increased fibronectin, collagen and tenascin-C accompany breast tumorigenesis and participate in tumor progression, invasion and metastasis." (PMID 28187162, 2017). "Tenascin-C promotes the survival of tumor stem cells, inhibits immune surveillance, stimulates angiogenesis, proliferation, invasiveness, and metastasis of tumor cells." (PMID 29112161, 2017). "The results suggested that JNK, FAK and p-PaxillinS178 were required for TNC-induced motility and adhesion in tumour cells." (PMID 29088796, 2017). "After knockdown of TNC in tumour cells, the expression of phosphorylated JNK and c-Jun were significantly decreased compared to siControl cells." (PMID 29088796, 2017). "TNC overexpression has repeatedly been observed in various types of tumours, especially in the front of invasive tumours." (PMID 29088796, 2017). "In contrast, the expression of tenascin-C in the tumor bulk of esophageal adenocarcinoma tumors was related to higher TNM-stage." (PMID 28978001, 2017). "Expression in the invasive front was higher than in tumor bulk stroma mean difference of tenascin-C expression being 0.7 (95% CI 0.3-1.1; p<0.001) and that of fibronectin 0.7 (95% CI 0.4-1.0; p<0.001)." (PMID 28978001, 2017). "To investigate the clinical significance of ITGA3, ITGA6, and TNC in HNSCC, we analysed their associations with tumor stage and lymph node stage using the TCGA-PRAD database." (PMID 28415821, 2017). "Tenascin-C is able to influence cancer growth by affecting cell adhesion and migration, but also by influencing the expression of tumor suppressor genes, oncogenes and genes involved in the maintenance of genomic stability." (PMID 28978001, 2017). "It has also been reported that cancer cells in micrometastases act as the main source of tenascin-C in the tumor until the tumor stroma can take over the tenascin-C production." (PMID 28978001, 2017). "Both tenascin-C and -W can be expressed in tumor stroma usually at similar percentages, being most likely produced by CAFs." (PMID 29112161, 2017). "Aptamers binding to tenascin-C, a protein found on tumor cells, was detected by passing tenascin-C extracted from tumor cells through a flow cell containing the immobilized aptamers." (PMID 29186905, 2017). "Tenascin-C expression was remarkably higher in ESCC than in adjacent non-tumor esophageal epithelium (p < 0.001)." (PMID 26731558, 2016). "In the tumor cells, the ability of Syn4 to bind to the fibronectin is competitively blocked by tenascin-C in integrin signaling, resulting in the proliferation of tumor cells." (PMID 27143125, 2016). "Tenascin C expression correlated moderately to strongly with the level of the proliferation marker Ki-67 in the tumor tissue." (PMID 27409604, 2016). "Depending on the tumor type, the findings of Tenascin-C serum levels and linkage to clinical parameter are variable." (PMID 26967391, 2016). "PF-EPN-A tumors were also characterized by tenascin-C (TNC) expression and tenascin-C has been suggested as candidate gene on 9q, involved in tumor progression." (PMID 27550150, 2016). "TNC has been proposed as a tumor marker being involved in malignant cell birth, proliferation, migration and epithelial-mesenchymal transition, angiogenesis, metastasis and evasion from therapy." (PMID 27612200, 2016). "Several studies have investigated the expression of Tenascin-C in various solid tumors and tumor microenvironments and supposed a functional role in tumor progression, migration and the formation of metastases." (PMID 26967391, 2016). "Tenascin-C has been suggested to be a predictor or biomarker of tumor invasion, metastasis, and survival in numerous malignant cancers, and has been investigated as a therapy target." (PMID 26731558, 2016). "Another functional role of Tenascin-C is immune-modulatory; it inhibits the proliferation of blood lymphocytes in vitro and interferon-gamma production by tumor-infiltrating lymphocytes isolated from NSCLC specimens." (PMID 26967391, 2016).
tumor (continued). "Our results indicate that tumor cells adjust their 3D microenvironment by modulating secretion of FN and Tenascin-C (TNC), thereby blunting the effects of MAPK pathway inhibition." (PMID 26944546, 2016). "The sensitivity (74%) and specificity (57%) of Tenascin-C was clearly inferior to the most frequently used tumor markers for NSCLC, SCCA, NES or CEA." (PMID 26967391, 2016). "In most cases, the expression of tenascin C correlates with the tumor grade and is indicative of a worse prognosis." (PMID 27409604, 2016). "Tenascin C is an extracellular glycoprotein complex expressed by a variety of cells including epithelial, stromal, and tumor cells." (PMID 27409604, 2016). "The relationship between tenascin C expression and tumor proliferation needs to be further investigated." (PMID 27409604, 2016). "Transfected cells were plated into wells coated with Matrigel, tenascin-C, and fibronectin to more closely mimic the in vivo tumor cell environment." (PMID 25837326, 2015). "This tenascin-C aptamer has the advantage of low accumulation in the liver and kidneys, resulting in high tumor-to-background ratios." (PMID 28536411, 2015). "Tenascin C expression is restricted to connective tissues and interestingly stem cell niches in adult tissues but is very prominent in tumor tissue." (PMID 26539408, 2015). "The initial engraftment of tumor cells at secondary sites is also critically influenced by tenascin C." (PMID 26539408, 2015). "The human monoclonal antibody stained patient-derived tumor sections with high specificity confirming the restricted expression of tenascin C to cancerous tissue." (PMID 26539408, 2015). "The glycoprotein tenascin C (TNC), a protein that inhibits the interaction between cell–ECM, was shown to be a target of miR-355, and loss of miR-355 potentiated tumor cells’ metastatic abilities." (PMID 24959422, 2014). "In our previous study, the key component of SCN, sulfatide, was demonstrated to mediate the binding and endocytic uptake of SCN in tumor cells via the interaction with tenascin-C." (PMID 25072631, 2014). "Several reports have recently revealed that the ECM proteins fibronectin, tenascin-C, periostin and versican play essential roles as components of the metastatic niche for tumor-initiating cells that invade the lungs." (PMID 23951338, 2013). "According to Jones and Jones revealed that TNC is encoded as an ECM protein (tenascin-C) and the over-expression of this gene would enhance the tumor cell proliferation and invasion in tumorigenesis." (PMID 23405089, 2013). "An additional mechanism by which Notch mediates tumor aggressiveness is by the induction of Tenascin-C – an extracellular glycoprotein which correlates with malignancy in glioblastoma and other cancers – by the Notch canonical co-activator RBPJκ." (PMID 23451269, 2013). "TNC is a component of the extracellular matrix, and the authors suggest that tumor-secreted TNC plays an important role in determining the metastasis initiating capacity of a cell." (PMID 22295241, 2012). "Together with another ECM protein-tenascin C–Postn plays a key role as metastasis niche component for breast-derived tumour-initiating cells that invade the lungs." (PMID 22966238, 2012). "Tenascin-C stimulates angiogenesis in ECs, mediates survival of tumor stem cells, enhances proliferation, invasiveness, and metastasis in tumor cells, and blocks immunosurveillance." (PMID 21941547, 2012). "We have previously demonstrated that sulfatide mediates the binding and endocytic uptake of SCL in tumor cells via the interaction with tenascin-C." (PMID 23145140, 2012). "The downregulation of tenascin C acts as a suppressor of the epithelial to mesenchymal transition, which is important in tumor invasion and metastasis." (PMID 22711317, 2012).